RN7SL262P (RNA, 7SL, cytoplasmic 262, pseudogene)
Gene: Miscellaneous RNA gene on chromosome X (49,152,651 to 49,152,944, forward strand). Ensembl gene ENSG00000265033.
Homologues: Orthologues: chimpanzee Metazoa_SRP (99% identical). Paralogues in human: RN7SL1 (85% identical), RN7SL2 (84% identical), RN7SL3 (83% identical), RN7SL230P (82% identical), RN7SL296P (81% identical), RN7SL45P (81% identical), RN7SL336P (80% identical), Metazoa_SRP (80% identical), RN7SL357P (80% identical), RN7SL473P (80% identical), RN7SL627P (80% identical), RN7SL630P (80% identical), and 701 more.